PI4KB (phosphatidylinositol 4-kinase beta)
Diseases named in the same sentence as PI4KB in open-access papers:
PI4KB is named in the same sentence as 32 diseases in open-access papers, as found by Europe PMC text mining. Sharing a sentence is not in itself a finding about the gene and the disease. The quoted sentences say what the papers report.
viral infection (5 papers, 2019 to 2025). "The inhibition of OsARF1 expression disrupts the recruitment of the P protein to PI4KB, thereby inhibiting viral infection." (PMID 40834074, 2025). "On the other hand, some viral proteins have been shown to interact with ACBD3 to drive the formation of large complexes, such as viral protein/ACBD3/PI4KB (phosphatidylinositol-4-kinase B), following viral infection." (PMID 39723831, 2025). "In conclusion, it would seem as if APOLs were evolutionary generated as instruments to limit viral infection through their involvement in PI4KB‐dependent autophagy and autophagy‐related apoptosis, following their strong induction by the virus‐activated TLR3/TRIF pathway." (PMID 32530132, 2021). "Thus, a cooperation with some other viral proteins can be required to increase the PI4KB activity during viral infection." (PMID 31381608, 2019). "However, despite this evidence it is not known whether the PI4KB controllers NCS‐1 and CALN‐1 participate in viral replication, and whether the effects of APOLs on viral infection involve the control of PI4KB." (PMID 32530132, 2021). "In addition, neither virus infection nor the expression of enterovirus 3A proteins alone elicited PI4KB recruitment in the absence of ACBD3." (PMID 30755512, 2019).
malaria (3 papers, 2022 to 2025). Malaria is a serious and sometimes fatal disease caused by a parasite that commonly infects a certain type of mosquito which feeds on humans. "Here, we show the selection of nonsynonymous mutations in malaria parasites' druggable kinases: the PANK1, DAGK, and PI4Kβ." (PMID 38915420, 2022). "We reveal sequence conservation and unique ligand-binding motifs in the CK, PANK1, DAGK, PI4Kβ, and CDPK1 across malaria species." (PMID 38915420, 2022).
breast carcinoma (2 papers, 2022 to 2023). "In this context, it is worth noting that ACBD3, Arf1, PI4Kβ and Rab4A all have been implicated in breast cancer progression and prognosis and found to be coordinately regulated in the same region of chromosome 1q." (PMID 37048152, 2023). "Of interest to this study, PI4KB is highly amplified in a subset of breast cancers and contributes to their oncogenic phenotype (Waugh, 2014)." (PMID 35651652, 2022). "We demonstrate that MMV652103 potently inhibits the oncogenic PI4KB and PIK3C2G lipid kinases, is selectively cytotoxic to MCF7 and T47D estrogen receptor positive breast cancer cells and inhibits their ability to survive and migrate." (PMID 35651652, 2022).
enterovirus infection (2 papers, 2023 to 2025). "During enterovirus infection, ACBD3 recruits PI4KB to RNA replication sites to promote the synthesis of the phosphatidylinositol-4-phosphate (PI4P) lipids that are critical for the enteroviral RNA polymerase." (PMID 40207930, 2025). "Interestingly, we show that despite ACBD3’s well-characterized role in enterovirus infection, it promotes flavivirus infection with a different mechanism not related to PI4KB recruitment and PI4P synthesis." (PMID 40207930, 2025).
lung carcinoma (2 papers, 2023 to 2025). "In contrast, mesenchymal lung cancer cells are less reliant on the PI4KB pathway but highly dependent on NOTCH signaling for metastatic dissemination." (PMID 40189704, 2025). "Here, we show that miR-34a regulates PI4KB activity through this mechanism and that ZEB1 silences miR-34a and miR-182/-183 to coordinately inactivate PI4KB and increase PI4K2A levels, thereby executing a PI4KB-to-PI4K2A dependency switch that drives lung cancer progression." (PMID 36757799, 2023).
Autoimmunity (1 paper, 2019). The occurrence of an immune reaction against the organism's own cells or tissues. "Overexpression of Pi4kb due to the amplification observed might be contributing to autoimmunity." (PMID 31694869, 2019).
basal cell carcinoma (1 paper, 2021). A carcinoma involving the basal cells. "Hedgehog signaling is upregulated in basal cell carcinoma and medulloblastoma, and PI4KB may be a relevant target protein for pharmacological inhibition of Hh signaling." (PMID 34258297, 2021).
ciliopathy (1 paper, 2022). A genetic disorder of the cellular cilia or the cilia anchoring structures, the basal bodies, or of ciliary function. "Loss of phosphatidylinositol 4-kinase β (PI4KB), the main generator of PtdIns4P in the Golgi membrane, in zebrafish led to the absence of primary cilia and ciliopathy phenotypes including neuromasts, pronephric ducts, and edema." (PMID 36547473, 2022).
colorectal cancer (1 paper, 2025). A primary or metastatic malignant neoplasm that affects the colon or rectum. "Importantly, elevated PI4KB phosphorylation at S256 and T263 was observed in RAS-mutated cancer cells and colorectal cancer specimens." (PMID 40055523, 2025).
Flavivirus Infections (1 paper, 2025). Infections with viruses of the genus FLAVIVIRUS, family FLAVIVIRIDAE. "However, at 1.25 μM, the compound did not inhibit LGTV or TBEV replication in A549 cells, showing that PI4KB recruitment is not the proviral mechanism for ACBD3 in flavivirus infection." (PMID 40207930, 2025).
hepatoma (1 paper, 2011). "In this study, we used a T7 RNA polymerase-based expression system in Huh7 human hepatoma cells to study the roles of PI4KA and PI4KB on HCV membranous web assembly." (PMID 22022594, 2011).
Infertility (1 paper, 2020). "PI4KB (involved in actin formation), SOX2 (essential for early embryonic development) and DPY19L2 (causes infertility by impairing head elongation, PLCζ signalling, acrosome formation and by causing globospermia) were downregulated in crossbred males, in microarray." (PMID 32693775, 2020).
pancreatic cancer (1 paper, 2025). "Inhibition of MEK1/2 and PI4KB phosphorylation on S256 and T263 in combination effectively suppressed autophagy and inhibited the proliferation of RAS-mutant tumor cell lines, and tumor growth in xenograft and LSL-KrasG12D, p53F/F, Pdx1-Cre mice (KPC) pancreatic cancer models." (PMID 40055523, 2025). "Inhibition of PI4KB S256 and T263 phosphorylation led to a reduction in RINCAA activity and tumor growth in both xenograft and KPC models of pancreatic cancer, suggesting that targeting ULK1-mediated PI4KB phosphorylation could represent a promising therapeutic strategy for RAS-mutated cancers." (PMID 40055523, 2025).
schizophrenia (1 paper, 2021). A major psychotic disorder characterized by abnormalities in the perception or expression of reality. "Moreover, in addition to the relationship between the PI4KB activator NCS‐1 and schizophrenia, genetic and functional linkages were also observed between the PI4KB inhibitor CALN‐1 and schizophrenia." (PMID 32530132, 2021).
steatosis (1 paper, 2024). Increased lipid within the cytoplasm of cells. "If so, targeting PI4KB might be a very promising strategy to directly attenuate steatosis, inflammation and fibrosis in MASH." (PMID 38561547, 2024).
infection (11 papers, 2011 to 2025). The state of being infected such as from the introduction of a foreign agent such as serum, vaccine, antigenic substance or organism. "This work reveals the essential roles of functional coupling and high-order, multitiered epistasis conferred by mutations in PI4KB/OSBP-independent infection." (PMID 34468191, 2021). "In this study, we analyze the roles of the 2B-Q20H and 2C-M187V mutations in PI4KB/OSBP-independent infection." (PMID 34468191, 2021). "While PHB and APOLs seem to be part of an autophagy system linked to infection, PI4KB is likely to be associated with this system given involvement of this enzyme in both autophagy and viral replication." (PMID 32530132, 2021). "These mutations confer enhanced replication in PI4KB/OSBP-independent infection concomitantly with an increased ratio of viral plus-strand RNA to the minus-strand RNA." (PMID 34468191, 2021). "In RD(ΔPI4KB) cells (i.e., PI4KB/OSBP-independent infection), the 3A-R54W mutation conferred a small or almost invisible plaque phenotype (mutant 1)." (PMID 34468191, 2021). "Accordingly, PI4KB was found to be involved in autophagy linked to infection by group A Streptococcus." (PMID 32530132, 2021). "We compared the changes to Arf1, GBF1, and PI4KB localization caused by 3CD to corresponding changes caused by infection." (PMID 29782554, 2018). "Two independent lentiviral shRNA constructs targeting PI4KB were used to silence PI4KB in Huh7.5.1 cells, followed by infection with a Jc1/Gluc2A virus encoding a secreted Gaussia luciferase reporter." (PMID 22022594, 2011). "Therefore, we quantified the ratio of viral plus-strand RNA to the minus-strand RNA in PI4KB/OSBP-independent infection and analyzed the effects of the mutations on the ratio." (PMID 34468191, 2021). "To evaluate the importance of the four mutations (3A-R54W, 2C-M187V, 2B-F17L, and 2B-Q20H mutations) in infection, we first analyzed plaque phenotypes of PV(Mahoney) mutants with the mutations in wild type (WT) and PI4KB-knockout RD cells—RD(WT) and RD(ΔPI4KB) cells, respectively." (PMID 34468191, 2021). "Collectively, these results suggested that the 2B-Q20H mutation, but not the 2C-M187V mutation, could confer enhanced infectivity, viral growth, and viral spread in PI4KB/OSBP-independent infection via recessive epistasis between the 3A-R54W/2B-F17L mutations." (PMID 34468191, 2021). "Adaptation of PV in PI4KB/OSBP-independent infection reached a plateau after five passages with four mutations fixed, suggesting that the roles of the PI4KB/OSBP pathway in the infection could be largely defined in three steps with the 3A-R54W/2B-F17L/2B-Q20H mutations." (PMID 34468191, 2021). "The potential antiviral effects on PI4KB/OSBP-independent replication was analyzed in the infection of the ΔPI4KB-resistant (−2C) mutant in RD(ΔPI4KB) cells." (PMID 37112883, 2023). "In this study, we found that viral spread from infected cells is the bottleneck of the PV 3A-R54W mutant in PI4KB/OSBP-independent infection." (PMID 34468191, 2021). "Infection by EV causes extensive cellular reorganization, including a protein 3A-mediated generation of replication organelles and the recruitment of cellular proteins such as GBF1, ACBD3, and PI4KB, all supporting viral RNA synthesis and virion assembly." (PMID 35458499, 2022). "The 3A and 2B mutations could confer specific enhancement of the replication level and rate in PI4KB/OSBP-independent infection concomitantly with an increased ratio of the RNAs." (PMID 34468191, 2021). "The ratio of viral plus-strand RNA to the minus-strand RNA in PI4KB/OSBP-independent infection." (PMID 34468191, 2021). "The 2B-F17L mutation enhanced the infectivity without enhancing the replication rate or level in PI4KB/OSBP-independent infection via recessive epistasis between the 3A-R54W mutation." (PMID 34468191, 2021).
infection (continued). "Interestingly, we noticed a loss of the typical Golgi localization of PI4KB in EMCV-infected cells, suggesting that Golgi integrity might be affected upon EMCV infection." (PMID 26406250, 2015). "As previously shown, the CVB3 3A protein colocalized with ACBD3 and PI4KB throughout infection in infected HeLawt cells, which implies that both ACBD3 and PI4KB localize to CVB3 ROs." (PMID 30755512, 2019). "We used western blot analysis to evaluate the expression levels of PI4Kβ and ACBD3 over the course of the infection at several time points in control cells with DMSO and in presence of ITZ at 16 hpi." (PMID 30813555, 2019). "The replication rate/level and infectivity were not fully restored (about 30% to 40% of those in PI4KB/OSBP-dependent infection), consistent with observation in experimental evolution of an RNA virus with double mutations." (PMID 34468191, 2021). "Therefore, I propose that APOLs, PI4KB and PHB participate in the formation of autophagosomes induced by infection, particularly by viruses." (PMID 32530132, 2021). "Based on these observations, it was postulated that during infection, AiV 3A may displace TBC1D22 from ACBD3 to favour binding to PI4KB with a concomitant increased production of PI4P." (PMID 33799649, 2021). "Delayed RO formation under PI4KB inhibition has been observed in infection of a CVB3 3A mutant, thus enhancement of the replication rate might serve as a specific determinant for evolution toward PI4KB/OSBP-independent infection." (PMID 34468191, 2021).
cancer (10 papers, 2021 to 2025). A tumor composed of atypical neoplastic, often pleomorphic cells that invade other tissues. "Previous research studies suggest that PI4KB plays a role in driving the progression of various BC subtypes and is closely associated with increased cancer cell growth, invasiveness, and metastatic potential." (PMID 41377052, 2025). "We then sought to confirm a similar inhibition of RINCAA by PI4KB phosphorylation on S256 and T263 using cancer cells with endogenous RAS mutations." (PMID 40055523, 2025). "PI4KB is reported to be involved in the activation of Hh signaling, which is closely associated with cancer development." (PMID 34258297, 2021). "Our recent work has shown that PI4KB is amplified and functions as a cancer driver by heightening the secretion of pro-tumorigenic proteins in chromosome 1q-amplified LUAD (1q-LUAD)." (PMID 40189704, 2025). "The high specificity of short peptides like PI4KB-Peptide-1 in targeting RINCAA within RAS-mutant cancers, while maintaining immune activity, underscores their potential as a promising anticancer approach." (PMID 40055523, 2025). "A chromosome 1q21.3 amplicon harbors PI4KB and maintains cancer cell survival by activating a PI4KB-dependent secretome." (PMID 36757799, 2023). "Notably, PI4KB-Peptide-1 also suppressed cell proliferation in these cancer cells and exhibited comparable inhibitory effects on proliferation to chloroquine, a clinically used lysosomal inhibitor for autophagy inhibition, when combined with trametinib." (PMID 40055523, 2025). "In human cancer cell lines, PI4KB and ACBD3 are co-expressed." (PMID 40189704, 2025). "In immunoblot analysis, cancer cells with a RAS mutation contained a higher level of PI4KB phosphorylation on S256 and T263 than those without a RAS mutation." (PMID 40055523, 2025). "Given that ACBD3 interacts with PI4KB, we hypothesize that ACBD3 regulates cancer secretion by modulating the Golgi localization and activity of PI4KB." (PMID 40189704, 2025). "Considering that many PI4KB inhibitors have been developed to treat infectious diseases and cancer, such drugs could be repurposed to also treat MASH22." (PMID 38561547, 2024). "Among them, PI4KB was reported to be involved in the progression of cancers." (PMID 34258297, 2021). "Consistently, PI4KB-Peptide-1 mediated inhibition of PI4KB phosphorylation on S256 and T263, and therefore hindered RINCAA, including LC3 lipidation, autophagic flux determined by mitophagy, and WIPI2 puncta formation, across various RAS-mutated cancer cell lines." (PMID 40055523, 2025). "Furthermore, CM from ACBD3-deficient cells failed to recruit endothelial and cancer-associated fibroblast cells, a phenotype similar to that observed with PI4KB depletion, suggesting that ACBD3 functions, at least in part, by regulating secretion." (PMID 40189704, 2025). "Hence, PI4KB S256 and T263 phosphorylation may be a specific target of non-canonical autophagy for treating cancer with a RAS mutation." (PMID 40055523, 2025). "PI4KB small-molecule inhibitors induce apoptosis in 1q21.3-amplified, but not diploid, cancer cells." (PMID 36757799, 2023). "However, ACBD3 expression is decreased in the metastatic lesions of several cancer types, including NSCLC, a trend not observed in PI4KB expression levels." (PMID 40189704, 2025).
tumor (8 papers, 2021 to 2025). "The tumor inhibition effect of PI4KB-Peptide-1 surpasses that of chloroquine in immune-competent mice but is similar in immune-deficient mice, suggesting that PI4KB-Peptide-1 positively regulates the immune response more effectively than chloroquine." (PMID 40055523, 2025). "Besides, a mechanistic study demonstrated that circSLC6A6 could regulate tumor-associated signaling PI4KB/hedgehog pathway by sponging miR-497-5p." (PMID 34258297, 2021). "Our analysis revealed that PI4KB exhibited elevated expression levels in tumor tissues compared to normal tissues." (PMID 41377052, 2025). "Meanwhile, previous studies indicate that upregulation of PI4KB contributes to tumor development and progression and it is recognized as a potential prognostic indicator in BC." (PMID 41377052, 2025). "We verified that PI4KB is highly expressed in BC and found that downregulating its expression significantly suppressed tumor cell proliferation and motility." (PMID 41377052, 2025). "We generated HCT116 and SW620 cell lines stably overexpressing PI4KB-SA which were employed in the xenograft tumor experiment." (PMID 40055523, 2025). "In epithelial cancer cells with impaired NOTCH activity, ACBD3 primarily activates the PI4KB-driven secretory pathway to promote tumor growth, particularly in 1q-LUAD cells." (PMID 40189704, 2025). "High levels of PI4KB, PI4KA, and PI4K2A are associated with a poor prognosis in multiple tumor types and drive malignant progression through distinct mechanisms." (PMID 36757799, 2023). "Therefore, we subsequently determined the anti-neoplastic effects of PI4KB-SA expression using the subcutaneous xenograft tumor model." (PMID 40055523, 2025). "In addition, the combination of PI4KB-Peptide-1 and trametinib exhibited superior efficacy than chloroquine plus trametinib in inhibiting tumor growth, preserving normal pancreatic tissue, and extending survival periods." (PMID 40055523, 2025). "Notably, in contrast to chloroquine, PI4KB-Peptide-1 treatment alone decreased tumor growth and increased life span." (PMID 40055523, 2025). "In addition, miR-497-5p can as a sponge of circSLC6A6 to regulate tumor-related signaling pathway PI4KB/hedgehog and participate EC progress." (PMID 35259044, 2022). "In this in vitro tumor model, PI4KB-Peptide-1 expression in combination with trametinib dramatically blocked tumor growth, achieving equivalent (SW620) or superior (HCT116) tumor inhibitory effects to chloroquine combined with trametinib." (PMID 40055523, 2025). "Consistent with inhibiting PI4KB, PI4KB-SA expression reduced RINCAA (as revealed by LC3 and P62 staining), cell proliferation (Ki67), and tumor growth." (PMID 40055523, 2025). "Immunofluorescence and IHC assays confirmed that PI4KB-Peptide-1 expression curbed PI4KB phosphorylation on S256 and T263, RINCAA, cell proliferation, and tumor growth using xenograft model." (PMID 40055523, 2025). "Therefore, targeting PI4KB phosphorylation on S256 and T263 specifically inhibits RINCAA in RAS-mutant tumors and suppresses tumor growth." (PMID 40055523, 2025). "Among all the PI4P producing enzymes high tumor PI4KA and PI4K2B expression is associated with poor overall survival in mHSPC patients, whereas the expression of other two PI4P producing enzymes PI4KB and PI4K2A do not have statistical significance." (PMID 37996444, 2023).
PI4KB also shares sentences with these, for which no sentence is quoted: autoimmune disease (1 paper); breast tumor (1); cyst (1); endometrial cancer (1); hepatitis C (1); Huntington disease (1); infectious disease (1); medulloblastoma (1); metabolic disorders (1); neurological disorders (1); Non-Alcoholic Fatty Liver Disease (1); Obesity (1); Parkinsonism (1); SeSAME syndrome (1).